ETS1 (ETS proto-oncogene 1, transcription factor)
Diseases named in the same sentence as ETS1 in open-access papers (continued):
Sharing a sentence is not in itself a finding about the gene and the disease.
melanoma (continued). "The presence of ETS-1 in tissues derived from the neural crest, as melanocytes, might suggest the association of ETS-1 downregulation with the loss of the neural crest-associated phenotype during melanoma progression; nevertheless, our data speak in favor of its role in tumorigenesis." (PMID 21711453, 2011). "These associations between UV exposure, COP1, ETS1, BCL2, and melanoma apoptosis can provide new insight into fundamental melanoma pathophysiology, although no precise common mechanism between UVB exposure and decline in ARSB has been identified." (PMID 40562100, 2025). "ETS1 was identified as a key repressor of differentiation from TPEX into TEX, and CRISPR-Cas9 KO of ETS1 in activated CD8+ T cells improve anti-tumour efficacy in a suite of murine melanoma models, alongside increased cytokine production and cytotoxicity." (PMID 39399500, 2024). "This regulation could be achieved through a direct interaction of USP9X with the transcription factor ETS-1, preventing its proteasomal degradation by deubiquitination, and favoring its binding activity on NRAS promoters in melanoma cells." (PMID 35884430, 2022). "USP9X effects on ETS-1 stability appear not to extend to ETS-2, because USP9X knockdown in melanoma cells decreased ETS-1 protein levels but left ETS-2 unaffected." (PMID 34066106, 2021). "Our analysis implicates ETS1 and ELK1 in melanoma progression." (PMID 32079144, 2020). "In melanoma, both MEK and BRAF inhibition led to an induction of Ets-1 and NRAS expression that could be blocked by Usp9x inhibition." (PMID 28198367, 2017). "In summary, we report strong ETS1 expression in all nevi and melanomas but not normal melanocytes, providing a mechanism for how early TERT promoter mutations can be selective following oncogene activation." (PMID 29262649, 2017). "To obtain a more realistic interpretation, we considered ETS-1 post-translational modifications, rather than its total protein content, functionally relevant to melanoma." (PMID 21711453, 2011). "Nonetheless we cannot rule out the contribution of ETS family proteins besides ETS-1 to melanoma functional properties." (PMID 21711453, 2011). "Like ETS-1, c-KIT is directly targeted by miR-221/-222, being involved in normal cell growth and differentiation and repressed in metastatic melanomas." (PMID 21711453, 2011). "We then considered the possibility that this Ets-dominant negative protein interferes with other members of the ETS family, although we never observed any significant modulation of ETS-2, the closest member to ETS-1, in our melanoma samples (data not shown)." (PMID 21711453, 2011). "Specifically, we have shown that primary melanomas display significant amounts of ETS-1, barely or not phosphorylated at T38, whereas metastatic cells show the reverse pattern, with low levels of ETS-1 highly phosphorylated at T38." (PMID 21711453, 2011). "However it is unclear when in melanoma progression TERT and ETS1 proteins are expressed." (PMID 29262649, 2017). "We identify ETS-1 as a transcriptional regulator of miR-222, by direct binding to its promoter region, showing its functional shift, from negative to positive regulator, in early and advanced melanoma cells, respectively." (PMID 21711453, 2011). "Moreover, as reported and confirmed by our small interfering experiments showing c-JUN upregulation in Dsi-ETS-1-transfected melanoma cells (results not shown), c-ETS-1 is able to repress c-JUN, interfering with its strong transcriptional regulation." (PMID 21711453, 2011). "Moreover, the complex formed by ETS1 with p52 NF-κB, whose expression is specifically controlled by non-canonical NF-κB signalling, has been shown to bind selectively the mutant TERT promoter −146A thus promoting telomerase expression in glioblastoma and melanoma." (PMID 38033865, 2023).
melanoma (continued). "Notably, Ets-1 is induced by BRAF or MEK kinase inhibition, resulting in increased NRAS expression, which could be blocked by inactivation of Usp9x and therapeutic combination of Usp9x and MEK inhibitor fully suppressed melanoma growth." (PMID 28198367, 2017). "In metastatic melanoma, miR-222's promoter binds directly to ETS-1, where phosphorylation status influences its expression; conversely, non-phosphorylated ETS-1 in early melanoma suppresses miR-222 transcription." (PMID 39731171, 2024). "Usp9x KD reduced the stability of Ets-1 in both BRAF and NRAS mutant melanoma and decreased NRAS, but not total RAS protein levels." (PMID 28198367, 2017). "There was co-incident and significant overexpression of Usp9x, Ets-1 and NRAS in melanoma versus nevi, but Usp9x expression was not notably different between primary and metastatic melanoma." (PMID 28198367, 2017). "Co-immunoprecipitation studies show that SOX9 and Sp1 physically interact in melanoma cells, while silencing of SOX9 down-regulates ETS1, but not Sp1, in the same cells." (PMID 26885752, 2016).
ovarian carcinoma (41 papers, 2010 to 2026). A malignant neoplasm originating from the surface ovarian epithelium. "The up-regulation of ETS1 has been linked with various types of cancer (e.g., cervical, breast, and ovarian cancers), with a particular association with tumor development and invasion." (PMID 30020984, 2018). "Based on our findings, regarding the involvement of key MMPs towards the increased invasiveness associated with AKT activation in ovarian cancer cells, we attained the significant transcriptional activation of ETS‐1 oncogene." (PMID 28236660, 2017). "Chromatin immunoprecipitation analysis indicated that the levels of H3K9ac and ETS1 factors were significantly increased in BRCA1-mutated ovarian cancer tissue (Fig. 2Ai and Aii)." (PMID 24448423, 2014). "Although there was no significant change in the expression of PCAF, the expression levels of GCN5 and ETS1 factors were increased in BRCA1-mutated ovarian cancer." (PMID 24448423, 2014). "For this study, we chose to analyze our gene expression data using each of these approaches, and then compared the results to determine the most important pathway associations present following Ets-1 overexpression in 2008 ovarian cancer cells." (PMID 24280356, 2013). "Although we have focused on an ovarian cancer cell model for this study, the potential applicability of these findings is broad because Ets-1 overexpression is frequently associated with a wide spectrum of aggressive, advanced cancers." (PMID 24238102, 2013). "Ets-1 upregulation appears to associate specifically with more advanced, invasive tumors in breast and ovarian carcinomas, and is positively correlated with the enhanced metastatic potential of numerous cancers." (PMID 24280356, 2013). "The findings from our pathway-based network analyses illustrate the importance of Ets-1 expression in cancer-associated metabolic regulation in ovarian cancer." (PMID 24280356, 2013). "Of special interest are the associations found for nuclear AP2α and Ets1, as high levels of these transcription factors have been related to poor prognosis in ovarian cancer." (PMID 21694727, 2011). "We have previously shown that increased production of intracellular reactive oxygen species in C13* cells, a cisplatin-resistant variant of 2008 ovarian carcinoma cells, correlated with an increase in Ets-1 mRNA and protein expression." (PMID 21042593, 2010). "The transcription factor erythroblastosis virus E26 oncogene homolog 1 (Ets-1) is a transcription factor associated with chemotherapeutic resistance in ovarian cancer cells since an increased expression of Ets-1 leads to a decreased sensitivity to cisplatin treatment." (PMID 38203758, 2024). "Our research group has previously established that the transcription factor v-ets erythroblastosis virus E26 oncogene homolog 1 (Ets-1) is associated with chemotherapeutic resistance in ovarian cancer cells, whereby increased expression of Ets-1 results in decreased sensitivity to cisplatin." (PMID 24238102, 2013). "In the present study, we discovered that ETS1 was highly expressed in ovarian cancer omental metastases and that ETS1 could stimulate the proliferation, invasion, and migration of ovarian cancer cells, indicating that ETS1 was implicated in ovarian cancer omental metastases." (PMID 36477408, 2022). "At the same time, ETS1 was shown to stimulate the secretion of larger exosomes from ovarian cancer cells." (PMID 41516338, 2026). "It has been found that the overexpression of Ets-1 in the human ovarian carcinoma cell line 2008 decreased intracellular ROS and increased intracellular GSH, GPX antioxidant activity, and SLC7A11 expression and activity." (PMID 38203758, 2024). "Ovarian cancer cells overexpressing ETS1 secrete exosomes that are more easily internalized by macrophages, promoting M2 polarization to facilitate tumor cell metastasis to the omentum." (PMID 38195554, 2024).
ovarian carcinoma (continued). "Here, we demonstrated that ETS1-overexpressing ovarian cancer cells secreted larger exosomes with higher laminin levels." (PMID 36477408, 2022). "Our findings demonstrate that ETS1-overexpressing ovarian cancer cells can generate larger exosomes with higher laminin levels." (PMID 36477408, 2022). "Taken together, our findings indicate that the interaction of omental macrophages with ETS1-regulated exosomes affects omental metastasis in ovarian cancer." (PMID 36477408, 2022). "Using the Transwell assay, we discovered that ETS1 downregulation greatly decreased ovarian cancer cell migration and invasion capacity, whereas ETS1 overexpression enhanced ovarian cancer cell migration and invasion." (PMID 36477408, 2022). "To investigate the influence of ETS1 on the secretion and composition of exosomes generated from ovarian cancer cells, we overexpressed ETS1 in ovarian cancer cells using the lentiviral vector LV-ETS1." (PMID 36477408, 2022). "To confirm the significance of ETS1 expression for omental metastasis of ovarian cancer, we analyzed differentially expressed genes in the GSE178913 database, including five pairs of primary tumors and their corresponding omental metastases." (PMID 36477408, 2022). "To clarify the clinical significance of ETS1 in ovarian cancer, we investigated the correlation between ETS1 expression and clinicopathological characteristics in 90 ovarian cancer samples." (PMID 36477408, 2022). "Next, we investigated why ETS1 induced the uptake of ovarian cancer exosomes by omental macrophages." (PMID 36477408, 2022). "Si-ETS1 and pcDNA-ETS1 efficiently knocked down and overexpressed ETS1 in ovarian cancer cells, respectively." (PMID 36477408, 2022). "Exosomes released from ETS1-overexpressing ovarian cancer cells were specifically attractive to omental macrophages." (PMID 36477408, 2022). "ETS1 is an essential regulator of ovarian cancer metastasis, and its mRNA expression is related to the prognosis of patients with ovarian cancer." (PMID 36477408, 2022). "Ets-1 was shown to promote higher intracellular GSH levels in resistant ovarian cancer and induce transcription of xCT, an important mediator of the antioxidant pathway." (PMID 35789155, 2022). "Exosomes released from stably ETS1-overexpressing ovarian cancer cells were collected for further research." (PMID 36477408, 2022). "The clinical significance of ETS1 in omental metastasis and the prognosis of patients with ovarian cancer were retrospectively investigated." (PMID 36477408, 2022). "Knockdown of endogenous GSK3β in ovarian cancer cells inhibited both phospho-ETS1 and MMP-9 expression." (PMID 34023818, 2021). "ETS1 mRNA was positively correlated with KRT80 mRNA in 379 cases of ovarian cancer (P < 0.05, r = 0.161)." (PMID 34659572, 2021). "Specific polyclonal antibodies against phospho-ETS1 Thr265, Ser269 were generated to investigate its immunohistochemical expression in ovarian cancer tissues." (PMID 34023818, 2021). "According to the earlier data, HIF1α regulates the expression of the ETS1 gene in PA1 ovarian cancer cells." (PMID 34136678, 2021). "These MMP (MMP2 and MMP9) genes are transcriptionally regulated by different transcription factors, but most importantly ETS1 has been proposed as a promising factor in this regard especially in epithelial ovarian cancer." (PMID 34136678, 2021). "Upon generation of a specific antibody against phosphorylated ETS1, we demonstrated that phospho-ETS1 immunohistochemical expression in ovarian cancer specimens was correlated with that of MMP-9." (PMID 34023818, 2021). "We subsequently analyzed the expression of phospho-ETS1 in nine different ovarian cancer cell lines." (PMID 34023818, 2021). "To find the importance of ETS1 in ovarian cancer, we performed TCGA data mining and found that relative to other cancers, ovarian cancer is most affected by ETS1 gain of function." (PMID 34136678, 2021).
ovarian carcinoma (continued). "Considering all, our study suggests that glutamine plays a very significant role in migration and invasion in ovarian cancer cells and ETS1 plays a key role in inducing such oncogenic parameters." (PMID 34136678, 2021). "We conclude that the GSK3β/ETS1/MMP-9 axis regulates the biological aggressiveness of ovarian cancer." (PMID 34023818, 2021). "ETS1 has also been reported to potentially function as an angiogenic mediator in ovarian cancer and gastric cancer, which supports a role of ETS1 in controlling the angiogenesis in glioma." (PMID 31823805, 2019). "Together, our results suggest the possibility that SC66 inhibits invasiveness of ovarian cancer cells through the TGF-β1/Ets-1/MMP3 axis." (PMID 30975980, 2019). "An earlier study by Wilson and colleagues showed that ETS-1 levels increased and conferred cisplatin resistance in ovarian cancer." (PMID 31118072, 2019). "We also found Gi‐LPAR2 activation to be significantly responsible for ETS‐1‐mediated ovarian cancer tumorigenesis." (PMID 28236660, 2017). "Collectively, these data strongly suggest that ETS‐1 is a critical transcription factor to be induced in response to LPA‐signaling in ovarian cancer cells." (PMID 28236660, 2017). "Collectively, it can be suggested that transcriptional induction of ETS‐1 is directly regulated by HIF‐1α in ovarian cancer cells." (PMID 28236660, 2017). "Having shown that ETS‐1 is a key oncogenic factor in metabolic adaptations towards increased aggressive potential in ovarian cancer, we further wanted to identify its regulatory partners." (PMID 28236660, 2017). "We further analysed 12 subfamilies of the ETS group of transcription factors, and found that ETS‐1 is more significantly upregulated than other transcription factors in LPA‐induced ovarian cancer cells." (PMID 28236660, 2017). "To address the contribution of ETS‐1 to the shift in the bioenergetics observed in ovarian cancer cells upon LPA induction, we analyzed the effect of ETS‐1 knockdown in these cells." (PMID 28236660, 2017). "Given that LPAR1/2/3 expression is linked to invasion and metastasis in different cancer types, we investigated the specific receptor subtype responsible for ETS‐1 regulation in ovarian cancer cells." (PMID 28236660, 2017). "Together, these data certify the involvement of ETS‐1 to increase tumorigenesis in ovarian cancer cells." (PMID 28236660, 2017). "Overall, these data suggest LPAR2‐specific regulation of invasion in ovarian cancer cells through ETS‐1." (PMID 28236660, 2017). "ETS1 was shown to be overexpressed in C13 cells, a cisplatin-resistant derivate of 2008 ovarian cancer cells, and ectopic expression of ETS1 in 2008 cells conferred platinum resistance." (PMID 24624361, 2014). "We have shown that ovarian cancer cells that overexpress Ets-1 display decreased intracellular ROS, with increased intracellular GSH and glutathione peroxidase (GPX) antioxidant activity." (PMID 24238102, 2013). "In our previous study, we used a stable Ets-1 overexpression model in 2008 ovarian cancer cells to conduct whole genome microarray analysis, which we have more comprehensively examined here to further clarify the role of Ets-1 in ovarian tumorigenesis." (PMID 24280356, 2013). "The pathway analyses in this study have shown common enrichment in metabolic and oxidoreductase pathways in response to Ets-1 overexpression in ovarian cancer cells." (PMID 24280356, 2013). "Under oxidative stress, HIF-1α was decreased in response to SAS treatment only in cells that overexpress Ets-1 suggesting that GSH depletion regulates HIF-1α levels in ovarian cancer cells." (PMID 24238102, 2013). "We have previously shown that Ets-1 is transcriptionally activated by H2O2 in ovarian cancer cells via Nrf2 antioxidant response element binding within the Ets-1 promoter." (PMID 24280356, 2013).